EZH2 (enhancer of zeste 2 polycomb repressive complex 2 subunit)
Diseases named in the same sentence as EZH2 in open-access papers (continued):
Sharing a sentence is not in itself a finding about the gene and the disease.
lung cancer (continued). "In another study, pharmacologic inhibition of EZH2 induced radiation sensitivity in atypical teratoid/rhabdoid tumors in vitro, and silencing EZH2 with RNAi enhanced radiation sensitivity in lung cancer cells." (PMID 25051981, 2014). "Such explorations of the molecular mechanism of EZH2 will help us develop novel approaches to the diagnosis, treatment, and prevention of nonsmall-cell lung cancer." (PMID 24745014, 2014). "Some novel molecular targets in lung cancer include epidermal growth factor receptor and EZH2 combined with chemotherapy or radiotherapy." (PMID 24745014, 2014). "In lung cancer, EZH2 silencing with RNA interference (RNAi) enhances A549 and HTB-56 cell sensitivity to irradiation both in vitro and in vivo." (PMID 25159232, 2014). "In our current study, a basic mechanism for the anticancer effect of EZH2 silencing with RNAi was provided in human lung cancer cells." (PMID 24745014, 2014). "EZH2 overexpression is associated with a poor prognosis in lung cancer, and the knockdown of EZH2 expression decreases the growth and invasion of lung cancer cells." (PMID 24348521, 2013). "miR-212 exerts a pro-apoptotic effect in lung cancer cells by targeting the anti-apoptotic gene PED, and inhibition of HDAC and the histone methyltransferase EZH2 strongly reactivates miR-212 expression in lung cancer cells." (PMID 24348513, 2013). "Taken together these results suggest that the upregulation of EZH2 and G9a enzymes in lung cancer contributes to increase histone methylation and thus to decrease miR-212 expression levels." (PMID 22110741, 2011). "Consistent with upregulation of EZH2 in aggressive cancers, the clustering revealed high expression of EZH2 in cluster 1, which contained samples from highly aggressive blood and lung cancers." (PMID 21886846, 2011). "Polymorphisms and haplotypes associated with a reduced risk of NSCLC have been found in KMT6 (EZH2) and KMT8 (RIZ1), while in contrast, polymorphisms in KMT1B (SUV39H2) are associated with an increased lung cancer risk." (PMID 24212667, 2011). "Overexpression of Polycomb group (PcG) proteins, particularly EZH2, the catalytic component of Polycomb Repressive Complex 2 (PRC2), has been associated with the pathogenesis of lung cancer, frequently showing correlation with cancer progression and poor prognosis." (PMID 41677721, 2026). "EZH2 is an increasingly recognized therapeutic target for lung cancer." (PMID 41301413, 2025). "Overall, the molecular docking analysis indicated strong binding affinities between MA and several key proteins associated with lung cancer, including EGFR, MDM2, IGF1R, EZH2, and GSK3B, with binding energies below −10.0 kJ/mol, suggesting exceptional binding strength." (PMID 40070571, 2025). "EZH2 inhibitor GSK343 combined with gefitinib also reverses gefitinib resistance in lung cancer." (PMID 40028035, 2025). "Thus, EZH2 polycomb repressive complex 2 subunit inhibitors are proposed to target SCLC lung cancer." (PMID 39083441, 2025). "Notably, EZH2 exhibited the most stable interaction with MA, underscoring its potential as a therapeutic target for lung cancer." (PMID 40070571, 2025). "Histone methyltransferase EZH2 is overexpressed in lung cancer cells." (PMID 40642070, 2025). "Importantly, reducing EZH2 levels can slow tumor growth and enhance the effectiveness of anti-cancer drugs, making EZH2 inhibition a promising strategy in the fight against lung cancer." (PMID 40070571, 2025). "Lung cancer-secreted exosomal circPVT1 contributes to macrophage polarization modulation by downregulating miR-124-3p, thus facilitating the enhancement in lung cancer cells of proliferation, invasion, and migration by elevating EZH2 expression." (PMID 40443670, 2025).
lung cancer (continued). "In lung cancer, the N-myristoylation of enhancer of zeste homolog 2 (EZH2) facilitates the formation of LLPS droplets that concentrate the substrate signal transducer and transcription 3 (STAT3) activator, thereby increasing STAT3 signaling and driving cell proliferation." (PMID 40335986, 2025). "EZH2 and E‐cadherin protein expressions in lung cancer by immunohistochemical analysis." (PMID 39400978, 2024). "It has been found that EZH2 could promote lung cancer metastasis and macrophages infiltration through the up-regulation of CCL5, therefore inhibition of EZH2 could suppress lung cancer progression." (PMID 39065562, 2024). "In other words, NOP2 could enhance the stability of EZH2 mRNA in lung cancer cells through m5C modification." (PMID 39013911, 2024). "SCLC tissues had higher EZH2 and lower E‐cadherin expressions than other lung cancer tissues." (PMID 39400978, 2024). "In addition, NOP2 was found to play a crucial role in promoting lung cancer progression by enhancing the stability of EZH2 mRNA in an m5C-dependent manner, thereby facilitating epithelial–mesenchymal transition (EMT) in lung cancer cells." (PMID 39013911, 2024). "However, studies have suggested that EZH2 inhibition can increase genotoxic stress in other models, and this idea should be explored in lung cancer." (PMID 38265267, 2024). "Similarly, the expression level of EZH2 in brain metastases from lung cancer patients was significantly higher than that of adjacent tissues from lung cancer patients." (PMID 38764053, 2024). "To validate this hypothesis, we assessed the EZH2 mRNA expression in lung cancer cells using RT-qPCR." (PMID 39013911, 2024). "Similarly, the expression level of EZH2 in brain metastatic tissue samples of lung cancer patients with brain metastasis was significantly higher than that in adjacent tissue samples of lung cancer patients (p < 0.0001)." (PMID 38764053, 2024). "Notably, we present novel evidence that NOP2 promotes lung cancer progression by enhancing EZH2 expression through an m5C-dependent mechanism." (PMID 39013911, 2024). "Targeting EZH2 myristoylation emerges as a novel lung cancer treatment strategy." (PMID 38481812, 2024). "In patients with brain metastasis of lung cancer, the genotype of G553C site of EZH2 gene is GG." (PMID 38764053, 2024). "Notably, the NOP2/EZH2 axis facilitated the malignant phenotype of lung cancer cells by inducing epithelial–mesenchymal transition (EMT) both in vitro and in vivo." (PMID 39013911, 2024). "However, treatment with GSK126 alone did not impact cell proliferation in these cells, leading the authors to suggest that EZH2 has dual roles at different stages of lung cancer depending on KRAS." (PMID 38036730, 2023). "Furthermore, it was shown that FAK inhibition leads to senescence in lung cancer involving the downregulation of EZH2, suggesting a functional correlation of EZH2 and FAK in non-small cell lung cancer." (PMID 38067205, 2023). "Our data suggest that in KRAS-driven lung cancers, a PRC2-deficient state, either occurring naturally or through EZH2 inhibition, may be vulnerable to BET inhibition." (PMID 36670102, 2023). "Recently, several studies explored the relationship of EZH2 and PD-L1 in lung cancers." (PMID 36532284, 2022). "Moreover, they showed that in NCI-H1299, NCI-H23, and NCI-H460 lung cancer cell lines, EZH2 silencing sensitized cells to cisplatin-induced apoptosis." (PMID 36230683, 2022). "The downregulation of EZH2 in lung cancer cells by miRNAs is mediated by its binding to 3′-UTR." (PMID 35236381, 2022). "Moreover, our IHC analysis revealed that the EZH2-mediated signaling cascade is spatially correlated with active FAK signaling in lung cancer tissues and cell lines." (PMID 36009484, 2022). "Increasing evidence suggests that EZH2 upregulation is in favor of lung cancer progression." (PMID 35236381, 2022). "A recent experiment has shown how miRNA/EZH2 axis can modulate EMT in lung cancer cells." (PMID 35236381, 2022).
lung cancer (continued). "The results of our experiments indicated that FAK activity might regulate EZH2-mediated signaling in lung cancer cells." (PMID 36009484, 2022). "LncRNA MSTO2P promotes lung cancer cell proliferation and autophagy by upregulating EZH2." (PMID 36105077, 2022). "A recent experiment has shown that lncRNA SVUGP2 is downregulated by EZH2 in lung cancer cells." (PMID 35236381, 2022). "On the other hand, there are miRNAs capable of regulating EZH2 expression in lung cancer." (PMID 35236381, 2022). "Silencing of EZH2 by either siRNA or inhibitors sensitized the lung cancer cells to gefitinib." (PMID 34405017, 2021). "It has been recognized that it can inhibit tumor proliferation by regulating several target genes, for example, miR-101 can directly inhibit cell proliferation by reducing the expression of zeste homolog 2 (EZH2) enhancer in lung cancer and embryonic rhabdomyosarcoma (eRMS)." (PMID 34658308, 2021). "Furthermore, the expression level of LAT1 and EZH2 was correlated with a less differentiated state in the tumorspheres of lung cancer cells." (PMID 34681614, 2021). "In addition, curcumin has been shown to inhibit the expression of enhancer of zeste homolog 2 (EZH2) in lung cancer cells, which was followed by a decrease in the expression of the Notch 1 gene." (PMID 34572272, 2021). "Previous data have showed that EZH2 regulates immune escape of lung cancer through HIF1A." (PMID 34838012, 2021). "To determine whether cytoplasmic EZH2 is frequent in lung cancer lines, we evaluated six additional lines that express DLC1 mRNA, three of which resemble A549 in not having readily detectable levels of endogenous DLC1 protein." (PMID 34862367, 2021). "Long Intergenic Non-Protein Coding RNA 665 (LINC00665) could also induce TKI resistance and promote the invasive ability of lung cancer cells by interacting with EZH2 and activating the AKT pathway." (PMID 34692550, 2021). "It was suggested that LINC00511 could promote the proliferation, invasiveness, metastasis but decreased apoptosis of lung cancer cells by interacting EZH2 to suppress p57 expression via the methylation of lysine 27 on histone H3 of p57 gene." (PMID 32713253, 2020). "It has been found that knocking down EZH2 or inhibiting its methyltransferase activity can result in the activation of retinoid X receptor α (RXRα) genes, which inhibit the transcription of Lat1 in lung cancer H1299 cells." (PMID 32448308, 2020). "Studies have shown that the expression of EZH2 is detected in lung precancerous lesions, which indicates that EZH2 may also play a role in the diagnosis of lung cancer." (PMID 33299862, 2020). "However, the effect of EZH2 on macrophages infiltration, cell invasion, and migration of lung cancer remains to be investigated." (PMID 31855281, 2020). "In addition, EZH2 also plays an important role in promoting lung cancer evolution by interacting with multiple lncRNAs, such as lncRNA 0051142, NEAT43, and TUG144." (PMID 33299646, 2020). "Therefore, we scoped to investigate the role of EZH2 in tumor cell behavior and in macrophage chemotaxis to evaluate the involvement of EZH2 in lung cancer." (PMID 31855281, 2020). "However, the functional role of EZH2 on macrophage recruitment in lung cancer remains to be investigated." (PMID 31855281, 2020). "This may suggest that the expression of EZH2 affects the prognosis of patients with lung cancer, and this relation may depend on the pathological type." (PMID 33299862, 2020). "Additionally, inhibition of EZH2 is also able to affect the macrophage activity in some other cancer types, such as suppressing macrophage infiltration in lung cancer and shifting microglia toward the M1 phenotype in glioblastoma." (PMID 33101367, 2020). "In summary, the current study demonstrated that EZH2 acted as a tumor promoter in lung cancer." (PMID 31855281, 2020).
lung cancer (continued). "We showed that lung cancer patients presenting high EZH2 mRNA levels or high KDM6B mRNA levels presented a significantly higher risk of early death (p = 3.4 ×10−5 and p = 4.8 × 10−5) compared to patients with lower EZH2 or KDM6B mRNA levels." (PMID 33291363, 2020). "The study that was not included in the meta-analysis also showed that the regulation of EZH2 expression is upregulated in lung cancer and that its expression is positively correlated with cancer stage and lymph node metastasis in patients with lung cancer." (PMID 33299862, 2020). "EZH2 is overexpressed in various tumors including lung cancer." (PMID 33276757, 2020). "In lung cancer, overexpression of DNMTs and EZH2 has been reported." (PMID 33256112, 2020). "In addition, results from ELISA showed that the expression of CCL5 in lung cancer tissues was decreased by EZH2 knockdown." (PMID 31855281, 2020). "Furthermore, it was reported that miR-101 inhibited cell metastasis by down-regulating EZH2 expression in lung cancer and osteosarcoma." (PMID 32005028, 2020). "Knockdown of SOX2OT in lung cancer decreased EZH2 expression and inhibited cell proliferation by inducing G2/M arrest, while knockdown of SOX2OT decreased SOX2 and OCT4 expression and inhibited stem cell pluripotency and tumourigenesis in oesophageal squamous cell carcinoma." (PMID 32019566, 2020). "Moreover, PCAF acetylates EZH2 at the K348 site promoting lung cancer tumorigenesis via stabilizing EZH2." (PMID 33308321, 2020). "Numerous studies have analyzed the correlation between EZH2 expression and lung cancer prognosis." (PMID 33276757, 2020). "The lncRNA MSTO2P promoted lung cancer cell proliferation and autophagy by upregulating EZH2." (PMID 32190662, 2020). "EZH2 is overexpressed in many human lung cancers, correlating with poor prognosis, and EZH2 may be responsible for the downregulation of SESN1 expression in lung cancers." (PMID 31857853, 2019). "Furthermore, several downstream molecules of EZH2 expression are reported to predict lung cancer prognosis." (PMID 31042721, 2019). "The difference in miR-101 copy number loss of SCLCs and NSCLCs, which indicates difference in miR-101 expressions may offer different mechanisms of EZH2 activation for different lung cancer types." (PMID 30894171, 2019). "For examples, either DZNep or GSK126 administration promoted the anti-tumor effect of TopoII inhibitor doxorubicin against BRG1 and EGFR mutant lung cancer, suggesting an opportunity for combination of traditional chemotherapy medicines and EZH2 inhibitors in NSCLC." (PMID 30002791, 2018). "This balance between KDM6A and EZH2 may be important in guiding therapeutic strategy in multiple diseases, including lung cancer." (PMID 30002791, 2018). "The oncogenic role of EZH2 in lung cancer was now clearly demonstrated by all these works, and several EZH2 inhibitors under clinical trials exhibited potential to be applied as novel targeted therapy or as an aid to current drug therapy for lung cancer (more detailed discussion in 5.1, 5.2)." (PMID 30002791, 2018). "For lung cancer, some EZH2 inhibitors stood out with promising therapeutic potentials." (PMID 30002791, 2018). "A recent study using a genetically engineered mouse model confirmed the oncogenic effect of EZH2 and showed that overexpression of EZH2 resulted in aberrant spread of H3K27me3 at the known tumor suppressors in lung cancer, thus pointing to EZH2 as a pressing target for cancer therapy." (PMID 30555330, 2018). "Furthermore, we observed a lung cancer-specific increase of the expression of the polycomb repressive factor EZH2." (PMID 28634396, 2017). "In addition, apoptotic effects of EZH2 inhibition have been reported in other cancers, including lung cancer." (PMID 28418882, 2017). "It has been reported that EZH2 is an oncogene involved in tumor progression, and miR-21 is also a biomarker for the tumorigenic processes, particularly for the pathological development of lung cancer." (PMID 29156731, 2017).
lung cancer (continued). "Abnormal expression of epigenetic enzymes includes overexpression of EZH2 (enhancer of zeste homolog 2), the catalytic subunit of the PRC2 repressive complex that methylates H3K27, associated with tumor progression and poor prognosis in lung cancer." (PMID 28804523, 2017). "Thus, we conducted a meta-analysis of all available studies relating EZH2 with the clinical outcome in patients with lung cancer." (PMID 26754405, 2016). "Moreover, an interesting study reported that specific KRAS mutation regulates EZH2 protein expression through the PI3K/AKT and/or MEK/ERK signaling pathways in lung cancer." (PMID 27494834, 2016). "To determine whether curcumin regulates EZH2 expression in lung cancer cells, we treated cell lines A549, NCI-H520, NCI-H1373, and NCI-H2170 with 6 μM of curcumin for 72 hours." (PMID 27049834, 2016). "Many studies have evaluated whether the overexpression of EZH2 may be a prognostic factor for survival in patients with lung cancer." (PMID 26754405, 2016). "Furthermore, our study suggested that DNMT1 was upstream of EZH2 and that interplay of DNMT1 and EZH2 were responsible for the overall responses of PPI in the inhibition of lung cancer cell growth." (PMID 27421653, 2016). "All reported the prognostic value of EZH2 status for survival in lung cancer patients." (PMID 26754405, 2016). "In addition to lung cancer, high EZH2 protein expression has been observed in several other malignant tumors, such as gastric cancer, pancreatic cancer and its expression has been reportedly correlated with poor survival in these patients." (PMID 27472460, 2016). "In conclusion, curcumin inhibits lung cancer growth through, at least in part, the inhibition of EZH2 and its reciprocally regulated molecule NOTCH1, suggesting that the molecules that are involved in the EZH2/NOTCH signaling pathway are potential therapeutic targets for lung cancer." (PMID 27049834, 2016). "The ectopic overexpression of miR-101 or miR-let 7c inhibited EZH2 expression in lung cancer cells." (PMID 27049834, 2016). "Because the 3′ UTR of EZH2 is directly targeted by several miRNAs, we next sought to determine whether curcumin altered the expression of miRNA(s), which regulate EZH2 in lung cancer cells." (PMID 27049834, 2016). "By upregulating miR-101, Curcumin could inhibit the expression of EZH2, thus inhibiting lung cancer growth and metastasis." (PMID 27835574, 2016). "Additionally, few reports have been published on the signaling pathway influencing the cell cycle after EZH2 silencing with siRNA in lung cancer cell lines." (PMID 24745014, 2014). "Therefore, our study explored the underlying mechanism and provides a clear link and direct evidence between EZH2 expression and induction of cell cycle arrest in human lung cancer." (PMID 24745014, 2014). "Undoubtedly, inhibition of either HOTAIR or EZH2 hinders progression of lung cancer." (PMID 25491133, 2014). "EZH2 staining was exclusively localized in the nuclei of lung cancer cells." (PMID 23300840, 2012). "In association with KMT6 (EZH2), menin has been shown to suppress lung adenocarcinoma cancer formation by repressing the growth factor pleiotrophin, a consequence of which is repression of lung cancer cell migration." (PMID 24212667, 2011). "Notably, EZH2 overexpression facilitated neuroendocrine development in a lung cancer mouse model, suggesting that EZH2 may be a universal mediator of this process." (PMID 41013839, 2025).